NDN (necdin, MAGE family member)
Description:
Growth suppressor that facilitates the entry of the cell into cell cycle arrest. Functionally similar to the retinoblastoma protein it binds to and represses the activity of cell-cycle-promoting proteins such as SV40 large T antigen, adenovirus E1A, and the transcription factor E2F. Also functions as a transcription factor and directly binds to specific guanosine-rich DNA sequences (By similarity).
Synonyms: HsT16328; PWCR
Tractability: PROTAC: ubiquitination databases record sites on it; its protein half-life has been measured.
Gene: Protein-coding gene on chromosome 15 (23,685,400 to 23,687,305, reverse strand). Ensembl gene ENSG00000182636.
Subcellular location: Perikaryon; Nucleus
Subcellular location (Human Protein Atlas): Cytosol; Nucleoplasm
Pathways (Reactome):
Immune System: Interleukin-4 and Interleukin-13 signaling
Gene Ontology:
Molecular function: protein binding; gamma-tubulin binding; promoter-specific chromatin binding
Biological process: negative regulation of transcription by RNA polymerase II
Cellular component: nucleoplasm; nucleus; centrosome; cytoplasm; cytosol; perikaryon; protein-containing complex
Genetic constraint (gnomAD): Loss-of-function variants: 1 observed, 9.92 expected, observed/expected ratio (o/e) 0.1, 90% interval 0.035 to 0.48. That is too few expected variants to judge how well the gene tolerates losing a copy. Missense variants: 465 observed, 411.76 expected, observed/expected ratio (o/e) 1.13, 90% interval 1.05 to 1.22. Synonymous variants: 245 observed, 179.2 expected, observed/expected ratio (o/e) 1.37, 90% interval 1.23 to 1.52.
Homologues: Orthologues: macaque NDN (97% identical), pig NDN (90% identical), dog NDN (88% identical), mouse Ndn (83% identical), rabbit NDN (82% identical), rat Ndn (78% identical), zebrafish ndnl2 (28% identical), Drosophila melanogaster MAGE (16% identical). Paralogues in human: MAGED2 (37% identical), MAGEL2 (35% identical), MAGED1 (34% identical), TRO (33% identical), MAGEF1 (33% identical), NSMCE3 (31% identical), MAGED4 (30% identical), MAGED4B (30% identical), MAGEE1 (30% identical), MAGEB16 (29% identical), MAGEB4 (28% identical), MAGEB1 (28% identical), and 25 more.
Diseases named in the same sentence as NDN in open-access papers:
NDN is named in the same sentence as 48 diseases in open-access papers, as found by Europe PMC text mining. Sharing a sentence is not in itself a finding about the gene and the disease. The quoted sentences say what the papers report.
Prader-Willi syndrome (21 papers, 2006 to 2026). "The gene encoding human NDN is located on chromosome 15q11, a region that is maternally imprinted in Prader-Willi syndrome, a neurogenetic disorder characterized by developmental delays and behavioral abnormalities." (PMID 26384308, 2015). "Human NDN is located in chromosome 15q11-12, a region responsible for the pathogenesis of the human neurodevelopmental disorder Prader-Willi syndrome." (PMID 24392139, 2014). "Similar ChIP in human cells shows that the CpG island of NDN and the Prader-Willi syndrome imprinting center (located in exon 1 of the SNRPN gene) carry H3K4me2 and H3K4me3 marks on the expressed paternal allele but not on the nonexpressed maternal allele." (PMID 23819640, 2013). "The SNRPN-SNURF and NDN loci map to the Prader-Willi syndrome region and are imprinted - expressed from the paternal allele in brain tissues." (PMID 19214233, 2009). "The deletion detected at 15q11.1-q11.2 with the aCGH showed that 106 genes are contained in this deletion including several OMIM genes, as well as NBEAP1, responsible for B cell leukemia in translocation events, and NDN, belonging to the contiguous genes responsible for the Prader Willi syndrome." (PMID 31474980, 2019). "Human necdin (NDN) and MAGEL2 genes are located at chromosome 15q11-12, a region responsible for the pathogenesis of the classic genomic imprinting-associated neurodevelopmental disorder Prader-Willi syndrome." (PMID 24911587, 2014). "MKRN3, MAGEL2 and NDN are three protein-coding genes located in the human 15q11-13 imprinted region, and the absence of the paternal contribution of this chromosomal region could lead to human Prader-Willi syndrome, characterized by neurogenetic disorders." (PMID 34359112, 2021). "NDN locates at 15q11.2 and is an intronless gene located in the Prader-Willi syndrome (PWS) deletion region." (PMID 31921798, 2019). "Prader-Willi syndrome (PWS) is a rare imprinting-related neurodevelopmental disorder caused by loss of paternally expressed genes within the chromosome 15q11-q13 region, including SNORD116, MAGEL2, and NDN." (PMID 41677631, 2026). "Deletion of genes from this region inherited from the father (MKRN3, MAGEL2, NDN, SNURF-SNPRN genes) leads to Prader-Willi syndrome (PWS)." (PMID 33375093, 2020). "Further investigation of OMIM database revealed that NDN and SNRPN are listed as candidate genes for Prader-Willi syndrome and that cryptorchidism is present frequently in the clinical picture of this syndrome." (PMID 30093884, 2018). "Prader-Willi Syndrome (PWS) is a neurodevelopmental disease involving imprinted genes, including NDN, which are only expressed from the paternally inherited allele, with the maternally inherited allele silent." (PMID 24039599, 2013). "Prader-Willi Syndrome (PWS) is a neurodevelopmental disease involving imprinted genes, including NDN, which are only expressed from the paternally inherited chromosome, the maternally inherited copy of the gene normally being silent." (PMID 24039599, 2013). "Deficiencies of other imprinted genes in the region, including MKRN3, MAGEL2 and/or NDN apparently play a role but not sufficient alone to generate the cardinal features recognized in Prader-Willi syndrome." (PMID 22043168, 2011).
Obesity (5 papers, 2016 to 2024). Accumulation of substantial excess body fat. "In adulthood, dysregulation of both MEST and NDN are implicated with the onset of obesity through adipose tissue expansion, suggesting potential postnatal health effects in energy balance regulation." (PMID 33003346, 2020). "Because NDN function is associated with cell growth, obesity and behavior, it can have effects in economically important traits in the production of cattle, yak, sheep, goat and buffalo." (PMID 30598832, 2018).
Angelman syndrome (4 papers, 2021 to 2025). A neurogenetic disorder characterized by severe intellectual deficit and distinct facial dysmorphic features. "MKRN3, MAGEL2 and NDN are three maternally imprinted genes in the human Prader-Willi and Angelman syndromes imprinted locus at 15q11-q13." (PMID 34359112, 2021). "Moreover, a cluster of genes in the BTA21 (GABRG3, MAGEL2, MKRN3, NDN, SNRPN, and SNURF) was significantly associated (FDR = 1.07 × 10−6) with the Prader-Willi and Angelman syndromes pathway in the PPI analysis." (PMID 35692843, 2022).
colorectal cancer (4 papers, 2017 to 2022). A primary or metastatic malignant neoplasm that affects the colon or rectum. "Previous studies have reported that NDN can inhibit the development of colorectal cancer, ovarian cancer, head and neck squamous cell carcinoma, breast cancer, and bladder cancer, and its expression is downregulated in most cancers." (PMID 35333696, 2022). "Moreover, several studies have reported low expression of NDN in colorectal cancer, ovarian cancer, head and neck squamous cell carcinoma, breast cancer, bladder cancer, and esophagus cancer." (PMID 35333696, 2022).
ovarian carcinoma (4 papers, 2016 to 2022). A malignant neoplasm originating from the surface ovarian epithelium. "The loss of NDN expression also promotes cancer cell motility, and invasion in ovarian cancer." (PMID 28521288, 2017). "Loss of NDN expression in ovarian cancers could be attributed to LOH in 28% of 18 informative cases and to hypermethylation of CpG sites 1 and 2 of NDN promoter in 23% and 30% of 43 ovarian cancers, respectively." (PMID 26689988, 2016). "NDN is a maternally imprinted gene, and it has been identified that tumor-specific hypermethylation in the key CpG islands was correlated with reduced expression of NDN in primary urothelial carcinoma and ovarian cancer." (PMID 28521288, 2017). "Recently, accumulating evidence has revealed that NDN is frequently down-regulated in various types of cancers such as urothelial cancer, ovarian cancer, breast cancer and prostate cancer, suggesting that this gene is a potential tumor suppressor." (PMID 28521288, 2017). "NDN was silenced in 5 ovarian cancer cell lines with heavy methylation in their NDN promoter regions." (PMID 26689988, 2016). "Apoptosis, autophagy, necrosis and senescence were measured in ovarian cancer cells transiently transfected with NDN cDNA or induced by exposure to doxycycline." (PMID 26689988, 2016). "Transient expression of NDN induced cleavage and activation of executioner caspases 3 and 7, indicative of apoptosis in ovarian cancer cells." (PMID 26689988, 2016). "We have found that NDN is consistently expressed in normal ovarian surface epithelial cells but is frequently downregulated in surgical specimens of ovarian cancers and cancer cell lines." (PMID 26689988, 2016). "As cell motility is essential for ovarian cancer metastasis, we used NDN-inducible cells to test the effect of necdin on cell motility and chemotaxis." (PMID 26689988, 2016). "Depletion of NDN in OVCA 432, an ovarian cancer cell line with relatively high NDN expression improved cell proliferation." (PMID 26689988, 2016). "In ovarian cancer tissues from 43 patients, all cases with promoter hypermethylation showed decreased NDN mRNA levels (top left quadrant)." (PMID 26689988, 2016). "Our data documents for the first time that re-expression of NDN inhibits growth and motility of ovarian cancer cells." (PMID 26689988, 2016). "NDN expression levels in 10 ovarian cancer cell lines were also measured using qPCR, and compared with pooled NOE." (PMID 26689988, 2016). "To evaluate its role in the function of ovarian cancers, we re-expressed NDN in SKOv3ip and HEY by transient transfection and also generated several inducible cell lines from SKOv3ip line." (PMID 26689988, 2016). "Re-expression of NDN decreased Bcl-2 levels and induced apoptosis, which significantly inhibited ovarian cancer cell growth in cell culture and in xenografts." (PMID 26689988, 2016). "Here we also report for the first time that NDN is dramatically downregulated in each of the ovarian cancer cell lines tested and in 73% of surgical specimens through both genetic and epigenetic mechanisms." (PMID 26689988, 2016). "To investigate the possible genetic and/or epigenetic mechanism(s) of NDN silencing, we measured the DNA methylation status and LOH in normal ovarian tissue and in ovarian cancers." (PMID 26689988, 2016). "NDN is a maternally imprinted gene consistently expressed in normal ovarian epithelium, is dramatically downregulated in the majority of ovarian cancers." (PMID 26689988, 2016). "Imprinting center methylation is critical for programing genomic imprinting event, but it may not be as important for NDN downregulation since only a tiny fraction of ovarian cancers exhibited IC hypermethylation." (PMID 26689988, 2016). "Whether NDN functions as a tumor suppressor gene in ovarian cancer or how it is downregulated has not previously been addressed." (PMID 26689988, 2016). "Little or no NDN expression could be detected in 73% of 351 epithelial ovarian cancers." (PMID 26689988, 2016).
breast carcinoma (3 papers, 2015 to 2022). "Our work demonstrates that several polymorphisms in NDN are significantly associated with clinical outcomes in breast cancer patients, and that these polymorphisms influence the function of NDN as a transcriptional regulator and metastasis suppressor." (PMID 26384308, 2015). "Haplotype analysis in a well-characterized breast cancer cohort revealed that NDN germline variation is associated with both NDN expression levels and patient outcome." (PMID 26384308, 2015). "In this study using a publically available breast cancer dataset, we demonstrate that NDN harbors polymorphisms associated with patient survival." (PMID 26384308, 2015). "To better understand how hereditary factors influence metastasis in breast cancer, we characterized NDN-mediated transcription." (PMID 26384308, 2015). "Specifically, we characterized associations between haplotypes in LD with human NDN and the expression level of c­-MYC in TCGA breast cancer cohort." (PMID 26384308, 2015). "Earlier studies have reported that the expression of NDN is decreased in many different cancer types in comparison to normal tissue, including breast cancer, suggesting that it acts as a tumor suppressor." (PMID 26384308, 2015). "We have demonstrated in the small, yet well characterized TCGA human breast cancer cohort that SNPs in putative regulatory regions are not only associated with the expression of NDN in primary breast tumors, but are also associated with markers of patient outcome and survival." (PMID 26384308, 2015).
hypogonadism (3 papers, 2021 to 2024). A disorder characterized by decreased function of the gonads. "MKRN3, NDN, and SNORD116, genes that are located in the PWS critical region, have been associated with GnRH secretion and hypothalamic dysfunction leading to hypogonadism." (PMID 34640379, 2021). "NDN is highly expressed in GnRH neurons, and its deletion in mice significantly reduces the quantity of hypothalamic GnRH neurons and recapitulates PWS-associated hypogonadism." (PMID 37685915, 2023).
Apnea (1 paper, 2024). Lack of breathing with no movement of the respiratory muscles and no exchange of air in the lungs. "Deletion outcomes vary by type (ORPHA ID: 98,793, ORPHA ID: 177,901), including type 2 genes such as SNORD116-1, SNRPN, SNORD115-1, OCA2, MAGEL2, NDN, and their role in the development of apnea." (PMID 38902749, 2024).
cervical adenocarcinoma (1 paper, 2021). An adenocarcinoma arising from the cervical epithelium. "We identified PIK3CA, NDN, GOLGA6L4, and BAIAP3 as SMGs in cervical adenocarcinoma and confirmed that NDN, GOLGA6L4, and BAIAP3 were novel SMGs." (PMID 33398034, 2021). "Fourth, in our study, after the evaluation of WES data in 20 cervical adenocarcinomas, six genes (i.e., PIK3CA, KRAS, TRAPPC12, NDN, GOLGA6L4, and BAIAP3) were predicted as driver genes that could promote tumor formation and development." (PMID 33398034, 2021).
colorectal tumors (1 paper, 2023). "In summary, our findings suggest that ZEB2, JAM2, NDN, and PPAP2A, along with the seven transcription factors related to these hub genes, may be associated with the response of colorectal tumors to chemoradiotherapy." (PMID 37636389, 2023).
encephalopathies (1 paper, 2025). "The genes NDN, SNRPN, and UBE3A are known for their association with Prader–Willi syndrome; GABRB and GABRA5 are associated with encephalopathies; OCA2 and HERC2 are linked to skin pigmentation." (PMID 40149731, 2025).
endometrial carcinoma (1 paper, 2022). A malignant tumor arising from the epithelium that lines the cavity of the uterine body. "NDN methylation was also observed in endometrial carcinoma by Liu." (PMID 35333696, 2022).
gestational diabetes (1 paper, 2020). Carbohydrate intolerance first diagnosed during pregnancy. "While few studies have linked NDN to pregnancy complications, the literature does support the involvement of MEST aberrations in various pregnancy-related outcomes, including in vitro fertilization (IVF)/intracytoplasmic sperm injections (ICSIs), viral load, gestational diabetes, and preeclampsia." (PMID 33003346, 2020).
glioma (1 paper, 2020). A benign or malignant brain and spinal cord tumor that arises from glial cells (astrocytes, oligodendrocytes, ependymal cells). "Our study revealed that NDN expression is downregulated in a coordinated manner with other T2Ms and higher expression of these T2Ms is associated with better patient prognosis in lower grade glioma." (PMID 33425727, 2020). "This analysis revealed that some MAGEs including MAGED subfamily are overexpressed, while most others including MAGEE1, MAGEE2, MAGEL2, MAGEH1, NDN, and TRO are downregulated in glioma." (PMID 33425727, 2020). "Further, other downregulated T2Ms in glioma, including MAGEE1, MAGEL2, TRO, and NDN also exhibited similar negative correlations with immune cell infiltration in LGG, while in GBM they showed a varying degree of positive correlations with infiltration of different immune cells." (PMID 33425727, 2020).
melanoma (1 paper, 2011). A malignant, usually aggressive tumor composed of atypical, neoplastic melanocytes. "NDN, the gene encoding Necdin, a negative growth regulator and member of the MAGE family of melanoma-associated tumor antigens, was identified as one candidate STAT3-regulated gene." (PMID 22046235, 2011).
Prader-Willi-like syndrome (1 paper, 2024). "For example, MAGEL2 deletion has been associated with Prader-Willi-like syndrome (ORPHA ID:398,069), including a UPD case (ORPHA ID:98,754) with a role for the SNRPN, OCA2, MAGEL2, and NDN genes." (PMID 38902749, 2024).
preeclampsia (1 paper, 2020). Preeclampsia is a hypertensive disorder of pregnancy that is characterized by new-onset hypertension with proteinuria presenting after 20 weeks of gestation, and depending on mild or severe forms may initially present with severe headache, visual disturbances, and hyperreflexia. "Our findings suggest downregulation of placental MEST and NDN expressions among preterm preeclampsia placentas." (PMID 33003346, 2020). "Following a comprehensive profile of imprinted gene expression across early and late onset preeclampsia cases and matched normotensive controls, we observed downregulated MEST and NDN expression levels in the early onset cases compared to preterm controls." (PMID 33003346, 2020). "Meanwhile, in later onset preeclampsia, this dysregulation in expression early in gestation is not triggered, and any temporal changes in MEST and NDN expression across gestation are not affected by later onset preeclampsia." (PMID 33003346, 2020).
psychosis (1 paper, 2022). "Other genes and snoRNAs that might play a role in the onset of psychosis are GABRG3, NDN, CYFIP1 and SNORD115." (PMID 35887798, 2022).
Schaaf-Yang syndrome (1 paper, 2025). "This cluster comprises the MKRN3, NDN, MAGEL2, and SNHG14 genes, the loss of function of which contributes to Prader-Willi and Schaaf-Yang syndromes." (PMID 40877933, 2025).
scoliosis (1 paper, 2019). A congenital or acquired spinal deformity characterized by lateral curvature of the spine. "Several DMRs related to scoliosis genes were tested, and the NDN: TSS-DMR (chr15:23932133-23932304, hg19) was confirmed in additional samples." (PMID 31921798, 2019).
sleep-disordered breathing (1 paper, 2025). "Combined deletion of Magel2 and Necdin (NdN-Magel2 double knockouts) results in a more pronounced phenotype, including exacerbated sleep-disordered breathing and apneic episodes." (PMID 41516228, 2025).
Stroke (1 paper, 2012). Sudden impairment of blood flow to a part of the brain due to occlusion or rupture of an artery to the brain. "NRP1 was observed to be elevated only in the core 3 d after stroke and NDN gene was down-regulated in the PI area at 24 h." (PMID 23284893, 2012).
urothelial carcinoma (1 paper, 2017). A malignant neoplasm derived from the transitional epithelium of the urinary tract (urinary bladder, ureter, urethra, or renal pelvis). "Indeed, NDN was down-regulated in urothelial carcinomas, promoted anoikis, repressed colony formation and anchorage-independent growth." (PMID 28521288, 2017).